LOXL2 (lysyl oxidase like 2)
Diseases named in the same sentence as LOXL2 in open-access papers (continued):
Sharing a sentence is not in itself a finding about the gene and the disease.
cancer (continued). "We first investigated the expression pattern of LOXL2 in the GEO dataset and in clinical samples of paired adjacent normal cervix and cancer tissues using quantitative polymerase chain reaction (qPCR) and immunohistochemical (IHC) assays." (PMID 32211324, 2020). "KDM3A transcriptome analysis revealed, in addition to Ets1 and MCAM, other genes previously implicated in the promotion of aggressive cancer properties, including the genes FYN, AXL, LOXL2 and PLAU." (PMID 32577157, 2020). "Then the CM of cancer cells and gingival fibroblasts were collected and concentrated by ultrafiltration and subjected to western blotting for LOXL2." (PMID 31086173, 2019). "Tracking cancer cells by IVIS after 3 weeks of injections of vehicle or PXS-S1C (30 mg/kg) demonstrated that inhibition of LOXL2 by PXS-S1C significantly decreased the distribution of cancer cells to other tissues." (PMID 31086173, 2019). "To the best of our knowledge, this is the first study that focuses on the radiosensitivity regulation effect of LOXL2 in cancer cells, although we focused mainly on CRPC cells." (PMID 30809541, 2019). "A monoclonal therapeutic antibody against LOXL2 (AB0023) was developed that only marginally reduced LOXL2 activity but showed efficacy in various pre-clinical models of cancer and fibrosis." (PMID 31130685, 2019). "The role of LOXL2 in fibrosis and cancer is well documented, however the specific enzymatic function of LOXL2 and LOXL3 during disease is less clear." (PMID 30536539, 2019). "Taken together, these results strongly suggest that LOXL2 is required for the efficient growth, VM formation, metastasis and progression of malignant tumours." (PMID 30506621, 2019). "Inhibition of LOXL2 activity dramatically changed the morphological appearance of LY2 cancer cells in the tongue and lymph nodes." (PMID 31086173, 2019). "Inhibition of LOXL2 attenuated cancer growth and lymph node metastases in the orthotopic tongue mouse models." (PMID 31086173, 2019). "Therapeutic approaches targeting LOXL2, by small molecule inhibitors or blocking antibodies, have demonstrated efficacy in fibrosis and cancer models." (PMID 31121900, 2019). "LOXL2 promotion of EMT has been reported in several cancer models previously, and the use of the novel selective LOXL2 inhibitor employed here resulting in apparent MET further supports the role of LOXL2 in cancer progression." (PMID 31086173, 2019). "Previous studies indicated that the miR29 family inhibits cancer cell migration and invasion by directly targeting LOXL2 in several cancers (e.g., renal cell carcinoma, cervical cell carcinoma, and lung, head and neck squamous cell carcinoma)." (PMID 30400792, 2018). "In general, clinical PC tissues tend to display enhanced LOXL2 staining in both cancer cells and the surrounding stroma." (PMID 29959362, 2018). "LOXL2 functions is crosslinking of collagen and elastin in the extracellular matrix (ECM), and overexpression of LOXL2 has involved in human pathogenesis, fibrosis and cancers." (PMID 29423074, 2018). "Lysyl oxidase (LOX) family genes, particularly lysyl oxidase-like protein 2 (LOXL2), have been implicated in carcinogenesis, metastasis, and the epithelial-to-mesenchymal transition (EMT) in various cancers." (PMID 29959362, 2018). "LOXL2 is increased in cancer and fibrosis as a consequence of aberrant signaling pathways and inflammatory mediators leading to remodeling of ECM." (PMID 28764769, 2017). "Recently, LOXL2 (lysyl oxidase-like 2) has been shown to represent a regulator of epithelial-mesenchymal transition (EMT) in different cancer types." (PMID 29113306, 2017). "Our data strongly support the continued development of selective LOXL2 small molecule inhibitors for use in the treatment of human cancers." (PMID 28199967, 2017).
cancer (continued). "To model increased LOX family activity in the tumors, and as LOX family members are secreted and can be produced by the cancer cells as well as by the stromal cells, we choose to add exogenously LOXL2 protein." (PMID 27050073, 2016). "Lysyl oxidase (LOX) and LOX-like protein 2 (LOXL2) produced by CAFs promote cross-linking of fibrillar type I collagen and result in matrix stiffening and consequent mechanotactic cues that support cancer cell invasion." (PMID 26954362, 2016). "LOX expression correlates with poor survival and is a therapeutic target for patients with certain cancers, while LOXL2 is a focus in the monitoring and treatment of fibrotic lung disease." (PMID 30155003, 2015). "Here, we investigated the effects of LOXL2 expression in normal mammary epithelial cells to gain insight into how LOXL2 mediates cancer progression." (PMID 23971878, 2013). "To demonstrate the usefulness of this assay we determined how inhibition of Loxl2 expression affects the invasiveness of cancer cells." (PMID 19948022, 2009). "Given the prominent role of LOXL2 in many types of cancer, selective inhibitors of LOXL2 may turn out to be useful therapeutic agents for the treatment and have distinct advantages for their long-term therapeutic management." (PMID 40148559, 2025). "We believe that selective nature-derived inhibition of LOXL2 may provide a better therapeutic approach for the treatment of cancer." (PMID 40148559, 2025). "Although the biological roles of LOXL2 in various cancer types have been established, the molecular mechanisms underlying LOXL2 in EC remain unclear." (PMID 39877633, 2025). "Therapeutically, LOX inhibition could concurrently benefit fibrosis and cancer treatment, such as LOXL2 inhibitors reducing ECM stiffness in fibrotic tumors to improve drug efficacy." (PMID 40661776, 2025). "In addition to its catalytic role, the pro-oncogenic effect of LOXL2 on some cancers is attributed to its intracellular functions, such as transcriptional regulation of EMT-related genes expression, and a scaffolding protein role." (PMID 38326908, 2024). "LOXL2 is an enzyme which stabilizes collagen crosslinking, whose enzyme activity has been reported to be closely correlated with a variety of diseases, such as cardiac fibrosis, Uterine hypertrophy and cancer." (PMID 38326908, 2024). "Besides, the secreted characteristics of the LOXL2 protein determine its promising role in cancer screening and prognostic evaluation, indicating that LOXL2 can be considered a predictive and prognostic indicator for specific types of malignancies." (PMID 38922489, 2024). "Therefore, immunotherapy in cancer patients with LOXL2 overexpression requires more factors for consideration in personalized medicine." (PMID 38922489, 2024). "In order to examine the prognostic value of LOXL2 in pan-cancer patients, we analyzed its expression in relation to patients’ outcomes, concentrating on overall survival (OS), progression-free interval (PFI), disease-free interval (DFI), and disease specific survival (DSS)." (PMID 38922489, 2024). "Consequently, the immune infiltration scores, stromal scores and Pearson correlation of LOXL2 expression in pan-cancer have been calculated via the ESTIMATE algorithm." (PMID 38922489, 2024). "Previous studies have revealed that the expression of LOXL2 is upregulated in highly invasive cancers, and that LOXL2 ultimately leads to epithelial–mesenchymal transition by suppressing the expression of E-cadherin, which is a protein involved in tight junction." (PMID 38398797, 2024). "We found that N-WASP mediates cancer progression by linking LOXL2 signaling to FAK signaling." (PMID 38560567, 2024). "We examined the genetic alteration of LOXL2 in various types of cancer." (PMID 38922489, 2024). "However, in cancer, different factors and signalling pathways can lead to the abnormal expression and mislocalisation of LOXL2." (PMID 37762708, 2023).
cancer (continued). "Although the biological functions of LOXL2 have been identified in a variety of cancer types, the molecular mechanisms of LOXL2 in ESCC are unknown." (PMID 36995521, 2023). "In summary, early cancer identification based on the use of LOXL2 as a biomarker may be of potential benefit in designing treatments and improving clinical outcomes, but further investigation and additional trials are clearly needed." (PMID 37762708, 2023). "Given the significant role of LOXL2 in numerous cancers, extensive efforts are underway to identify specific inhibitors that could potentially improve patient prognosis." (PMID 37762708, 2023). "In addition, LOXL2 participates in the initiation and progression of a diverse set of diseases including fibrosis and cancer metastasis, which is consistent with the critical roles of LOXL2 in tubulogenesis, matrix assembly, and angiogenesis." (PMID 37029269, 2023). "Furthermore, the development of genetically modified mouse models with silenced or overexpressed LOXL2 has enabled in-depth exploration of its in vivo role in various cancer models." (PMID 37762708, 2023). "Lastly, we discuss the potential prognostic and therapeutic values of LOXL2 in cancer." (PMID 37762708, 2023). "In addition, LOXL2 inhibition reduced the expression of cancer stemness markers and stemness by regulating MAPK signaling activity." (PMID 37737908, 2023). "Consequently, the dysregulation of LOXL2 has been associated with a spectrum of diseases, particularly those connected with ECM remodelling, such as fibrosis and cancer." (PMID 37550884, 2023). "In addition, ERFE was co-expressed with the genes involved in extracellular matrix (ECM) deposition and remodeling, including PXDN, COL4A1, and LOXL2 that are known to promote cancer invasion and metastasis." (PMID 36675239, 2023). "Regarding LOXL2, increasing evidence has accumulated showing its role in several human cancers." (PMID 37298909, 2023). "Therefore, we concluded that the LCN2/LOXL2/MMP9 ternary complex promoted the invasion of cancer cells by degrading laminin and type IV collagen." (PMID 37753805, 2023). "Altogether, our results suggest that LOXL2’s interaction with the candidate RBPs could alter cancer traits at different levels." (PMID 37298909, 2023). "This implies that inhibitors decreasing LOXL2 expression or activity may be useful therapeutic agents for the treatment of many types of cancer." (PMID 37298909, 2023). "Regarding the use of LOXL2 as a prognostic marker in cancer, few attempts have been made to date." (PMID 37762708, 2023). "LOXL2 associates with and catalyses H3K36ac deacetylation thus blocking H3K36ac-dependent transcription of genes, including MYC proto-oncogene, BHLH transcription factor (MYC), cyclin D1 (CCND1), HIF1A, and CD44, thereby restricting cancer cell proliferation." (PMID 37762708, 2023). "Thus, LOXL2-induced aldolase A activation via recruitment from the cytoskeleton is a rapid and efficient way for cancer cells to increase metabolic flux." (PMID 36209516, 2022). "Loxl2 also binds transcription factors in the nucleus to inhibit and promote the transcription of genes that play a role in age-related diseases ranging from cancers to cardiovascular diseases." (PMID 34734976, 2022). "Moreover, strong links have been found between LOXL2, metastasis, and higher mortality, and LOXL2 is a potential biomarker for cancer detection." (PMID 35205728, 2022). "In addition, there was a prevalence of promising preclinical data (utilizing the mouse LOXL2 antibody AB0023) in both cancers and organ fibrosis." (PMID 35205728, 2022). "First of all, the collagen-related parameters (length, width, and density), the expression and distribution area of COL I and III, and the expression of COL I/COL III, COL I area/COL III area, LOX and LOXL2 in cancer tissues were higher than those in normal tissues." (PMID 34335820, 2021).
cancer (continued). "Therefore, targeting this enzyme by a small molecule with the ability to block both intra- and extracellular LOXL2 would be a more effective approach to fight cancer progression and metastases." (PMID 33669630, 2021). "LOXL2 intracellular mechanisms are critical for cancer progression." (PMID 33669630, 2021). "Reportedly, LOXL2 is also vital regulator in cancer biology." (PMID 34308761, 2021). "Using this theoretical framework, we demonstrated the heterogeneity of LOXL2/stiffness and its implications on migrating cancer cells that could seed metastasis, the growth of secondary malignant tumors." (PMID 33807227, 2021). "It was hypothesized that possibly, both genetic and epigenetic mechanisms are involved in the modification of LOXL2 gene expression during cancer progression." (PMID 33639646, 2021). "Any alteration in cellular localization of LOXL-2 expression, whether it is from membranous to cytoplasmic or nuclear to cytoplasmic might be a prognostic sign depending on the organ affected by cancer." (PMID 33639646, 2021). "Moreover, the mRNA expressions of COL I, LOX, and LOXL2 in the cancer tissues of cold-constitution patients were higher than those in heat-constitution patients." (PMID 34335820, 2021). "LOX enzymes, and specifically LOXL2, are critical for cancer progression and metastases." (PMID 33669630, 2021). "The results strongly suggest that the LOXL2-HIF1α positive feedback loop might be a potential target for PDAC cancer therapy." (PMID 34836938, 2021). "Accumulated studies have documented the roles of LOXL2 in tumorigenesis, however, the relationship between LOXL2 and cancer metabolism remains unclear." (PMID 34836938, 2021). "LOXL2 is of particular interest in cancer biology as it is highly expressed in some tumors." (PMID 33669630, 2021). "It is found that LOXL2 is a promotor for the metastasis and invasion of cancer cells." (PMID 34970534, 2021). "LOXL2 has a complex role in cancers, which could be dependent or independent on its enzymatic activity, and at the same time, on its intracellular, extracellular, or intranuclear forms." (PMID 34836938, 2021). "The LOXL2 gene is considered as a promising target for cancer therapy." (PMID 33143259, 2020). "LOX and LOXL2 were significantly upregulated in RCC cell lines than other cancers." (PMID 32970930, 2020). "The majority of LOXL2 mechanistic studies have been focused on cancer." (PMID 32824630, 2020). "The role of LOX and LOXL2 has been well characterized in human cancers." (PMID 31121900, 2019). "LOXL2 has been therefore proposed as a novel marker for poor prognosis in distinct cancers types." (PMID 31130685, 2019). "LOXL2 has therefore been identified as an attractive target for cancer treatments." (PMID 29953488, 2018). "LOXL2, a member of the lysyl oxidase (LOX) family that encodes genes for copper-dependent amine oxidases, which participate in ECM stabilization by covalent cross-linking of collagen is strongly associated with cancer progression." (PMID 29503225, 2018). "Specific knockdown experiments demonstrated a stimulating role of LOXL2 during cancer progression." (PMID 30473751, 2018). "Knockdown of LOXL2 significantly inhibits cancer cell migration and invasion, indicating that LOXL2 could be a new therapeutic target in cancers." (PMID 29423074, 2018). "Also reciprocally, LOXL2 secreted by cancer cells has been shown to activate fibroblasts and increase LOXL2 production in the fibroblasts." (PMID 30701028, 2018). "Although studies in cancer biology have demonstrated that LOXL2 is able to regulate EMT via stabilisation of the EMT transcription factor Snail9,34, we found no significant reduction in E-Cadherin, which as a primary downstream target of Snail is generally repressed in EMT." (PMID 29930330, 2018).
cancer (continued). "This promiscuity, coupled with the lack of amenable sites for chemical modification, has rendered BAPN of little use for clinical drug development and detailed investigations into dissecting the differences in the functional role of LOX and/or LOXL2 in diseases such as cancer and fibrosis." (PMID 28199967, 2017). "The results confirmed that cancer cell-derived LOXL2 affected genes expression in HCC cells." (PMID 28449718, 2017). "Furthermore, many studies, including ours, investigated and showed the clinical relevance of LOXL2 expression during the metastasis of breast, gastric, liver, esophageal, and pancreatic cancers." (PMID 29113306, 2017). "Importantly, the antitumor miR-29 family (miR-29a/b/c) targeted LOXL2 and inhibited cancer cell migration and invasion." (PMID 28902136, 2017). "LOXL2 is necessary and sufficient to repress E‐cadherin under hypoxia condition in cancer." (PMID 28556501, 2017). "This study shows that RAMP3 may be specifically involved in many processes key for cancer metastasis and LOXL2 stimulates these actions upstream." (PMID 28845385, 2017). "Epidermal growth factor-like repeat and discoidin I-like domain-containing protein 3 (EDIL-3) and lysyl oxidase homolog 2 (LOXL2) were reported to facilitate cancer cell migration and pre-metastatic niche formation which were also down-regulated in the DET or DETD-35 responsive exosomes." (PMID 28706483, 2017). "LOXL2 has been emphasized in recent years because of its critical roles in carcinomas." (PMID 25254241, 2014). "These analyses suggest the functions of LOXL2 in carcinoma are multifaceted and complicated." (PMID 25254241, 2014). "LOXL2-induced cellular senescence was reported for the first time in pan-cancer within the present study, which may aid in related research and the development of new cancer therapies." (PMID 38922489, 2024). "Moreover, the expression of LOXL2 was remarkably related to PFI in 24 types of cancer." (PMID 38922489, 2024). "Besides, cancer patients with LOXL2 alternations of stable nuclear variant (SNV) had worse OS and PFS than those with no alterations in BRCA and CESC, while the copy number variation (CNV) of LOXL2 is associated with a worse prognosis in KIRP, UCEC, and BRCA." (PMID 38922489, 2024). "Moreover, LOXL2 plays an important role in regulating glucose metabolism in cancer metastasis." (PMID 37737908, 2023). "In addition, increasing knowledge about LOXL2 points to a role in several types of human cancer." (PMID 37298909, 2023). "Thus, many studies are targeting LOXL2 to inhibit the metastasis/invasion of cancer." (PMID 34970534, 2021). "Importantly, LOXL2 functions as an oncogene in various human cancers via diverse mechanisms." (PMID 34836938, 2021). "Moreover, LOXL2 may serve as a target in the development of antibodies or inhibitors for cancer therapeutics, as characterized in ClinicalTrials.gov NCT01323933." (PMID 32211324, 2020). "In addition, it is interesting to note that there is an association between LOXL2 protein expression and α-SMA-positive stromal fibroblasts in diverse types of solid tumours and that LOXL2 inhibition was efficacious in inhibiting cancer growth in both primary and metastatic xenograft models." (PMID 31216299, 2019). "Therefore, we hypothesized that LOXL2 inhibition may improve the survival of patients with PC by reducing cancer cell viability and increasing cellular sensitivity to chemotherapy." (PMID 29959362, 2018). "Thus, LOXL2 is likely to be an excellent drug target in many cancer types." (PMID 23971878, 2013). "Human OSCC TW2.6 (TW2.6/LOXL2) cells overexpressing LOXL2 exhibit enhanced migration, invasion, epithelial-mesenchymal transition (EMT), and cancer stem cell (CSC) phenotypes." (PMID 40061935, 2025). "Based on this as well as on multiple evidence indicating that CTSD and LOXL2 have pro-proliferative functions, inhibition of CTSD and LOXL2 have been suggested as a therapeutic approach for various cancers." (PMID 41185039, 2025).